CERS1 (ceramide synthase 1)
Diseases named in the same sentence as CERS1 in open-access papers (continued):
Sharing a sentence is not in itself a finding about the gene and the disease.
oral cancer (3 papers, 2021 to 2023). "CERS1 makes use of C18-acyl-CoA, which is linked to autophagic cell death in oral cancer cells." (PMID 37614280, 2023). "This study demonstrated that CERS1 knockdown was associated with endoplasmic reticulum (ER) stress and upregulated vascular endothelial growth factor A (VEGFA), which promoted oral cancer aggressiveness and chemotherapy drug resistance." (PMID 35954376, 2022). "By RT-PCR, we found that the expression of CERS1 in oral cancer tissues was lower than that in normal tissues (P < 0.001)." (PMID 33753723, 2021). "The aim of our study was to investigate the relationship between ceramide synthase 1 and oral cancer." (PMID 33753723, 2021). "Taken together, our study suggests that ceramide synthase 1 is downregulated in oral cancer and promotes the aggressiveness of oral squamous cell carcinoma and chemotherapeutic drug resistance." (PMID 33753723, 2021). "Cers1 knockout mice were more likely to develop oral cancer, which was consistent with the vitro experiments and other studies." (PMID 33753723, 2021). "This was also the first study to explore the effect of Cers1 on the occurrence and development of oral cancer in vivo." (PMID 33753723, 2021). "In this study, we found that the expression of ceramide synthase 1 was downregulated in oral cancer tissues and cell lines." (PMID 33753723, 2021). "Additionally, the knockdown of CERS1 in an oral cancer model resulted in reduced in vitro cell migration, proliferation, and invasion." (PMID 35954376, 2022). "Our data suggested that decreased levels of CERS1 might play important roles in oral cancer." (PMID 33753723, 2021). "Overall, downregulation of CERS1 plays a negative role in chemotherapy for oral cancer." (PMID 33753723, 2021). "The expression of CERS1 in non-malignant cells, such as HOK and DOK, was higher than that in oral cancer cell lines, including SCC25, CAL27, HSC-2, and HSC-3 (P < 0.05)." (PMID 33753723, 2021).
oral squamous cell carcinoma (3 papers, 2021 to 2023). "In a mouse oral squamous cell carcinoma model induced by 4-nitroquinolin-1-oxide, ceramide synthase 1 knockout was associated with the severity of oral malignant transformation." (PMID 33753723, 2021). "The table shows salivary CERS1 levels in oral squamous cell carcinoma, oral leukoplakia, and healthy individuals." (PMID 37614280, 2023). "Table showing the descriptive statistics of salivary CERS1 levels in oral squamous cell carcinoma, oral leukoplakia, and healthy individuals." (PMID 37614280, 2023). "The downregulation of CerS1 promotes the aggressiveness of oral squamous cell carcinoma and chemotherapy drug (cisplatin) resistance, while CerS1 overexpression induced sensitization to cisplatin via regulating cell death." (PMID 35565311, 2022). "Notably, studies have highlighted that reduced levels of CERS1 confer protection to oral squamous cell carcinoma (OSCC) cells against chemotherapeutic agents like cisplatin." (PMID 37614280, 2023). "However, the function of ceramide synthase 1, a key enzyme in C18 ceramide synthesis, in oral squamous cell carcinoma is still unclear." (PMID 33753723, 2021).
myoclonic epilepsy (2 papers, 2019). A group of epilepsy syndromes in which myoclonic seizures are a prominent feature. "Biallelic mutations in another ceramide synthase (CERS1), which catalyzes the formation of C18 ceramides and is highly expressed in the brain, causes a novel progressive myoclonic epilepsy associated with neurodegeneration." (PMID 30683667, 2019).
non-small cell lung carcinoma (2 papers, 2023 to 2025). A group of at least three distinct histological types of lung cancer, including non-small cell squamous cell carcinoma, adenocarcinoma, and large cell carcinoma. "We suggest that ceramide synthase 1 is an effective therapeutic target for non-small cell lung cancer patients with brain metastases." (PMID 37046655, 2023). "Ceramide synthase 1 participates in malignancy development, but its potential role in non-small cell lung cancer brain metastasis remains unclear." (PMID 37046655, 2023). "Using bioinformatics analysis and molecular biotechnology, we found that ceramide synthase 1 could inhibit non-small cell lung cancer brain metastasis in vivo and in vitro." (PMID 37046655, 2023).
Atrophy (1 paper, 2018). Any weakening or degeneration, especially through lack of use. "Genetic ablation of CerS1 causes neurodegeneration and cerebellar atrophy during development, and the lack of an effect of P053 on brain ceramides indicates that treatment with P053 is unlikely to cause neuronal atrophy." (PMID 30131496, 2018).
Becker muscular dystrophy (1 paper, 2022). Becker muscular dystrophy (BMD) is a neuromuscular disease characterized by progressive muscle wasting and weakness due to degeneration of skeletal, smooth and cardiac muscle. "Across multiple muscle diseases, including DMD, Becker muscular dystrophy (BMD), Emery-Dreifuss muscular dystrophy (EDMD), and facioscapulohumeral muscular dystrophy (FSHD), we found an almost universal up-regulation of sphingolipid biosynthetic enzymes, with the exception of CERS1." (PMID 35089797, 2022).
Cerebral ischemia (1 paper, 2023). Restriction of arterial blood supply to the brain associated with insufficient oxygenation to support the metabolic requirements of the tissue. "The accumulation of ceramides induced by SIRT3 is an important cause of cerebral ischemia–reperfusion injury, which is achieved through the activation of deacetylation of CerS1, CerS2, and CerS6 by SIRT3." (PMID 36374406, 2023). "However, an experiment conducted in 2016 showed that SIRT3 is activated by a currently unknown mechanism and increases the deacetylation level and activity of CerS1, CerS2, and CerS6 after cerebral ischemia–reperfusion." (PMID 36374406, 2023).
chronic heart failure (1 paper, 2020). "In humans, CerS1 and CerS5 mRNA expression declined not only age dependently but was also associated with chronic heart failure, suggesting that age‐ and critical illness‐related changes of specific Cer species contribute to myo‐pathological disorders." (PMID 31692231, 2020). "In comparison with a coeval healthy control cohort, a reduced CerS1 and CerS5 mRNA expression was found in muscle biopsies from aged patients suffering from chronic heart failure." (PMID 31692231, 2020). "Patients with chronic heart failure suffering from muscle weakness presented with decreased CerS1 and CerS5 expression, suggesting that CerS1 and CerS5 may also be linked to functional deficiencies of skeletal muscle in humans." (PMID 31692231, 2020). "Notably, reduced CerS1 and CerS5 mRNA expression was observed in chronically ill patients suffering from chronic heart failure, suggesting that decline of CerS1 and CerS5 gene expression is functionally relevant for the development of critical illness‐associated myopathies." (PMID 31692231, 2020). "Moreover, CerS1 and CerS5 mRNA expression was also reduced in muscle biopsies from patients in advanced stage of chronic heart failure (CHF) suffering from muscle wasting and frailty." (PMID 31692231, 2020).
COVID-19 (1 paper, 2023). A disease caused by infection with severe acute respiratory syndrome coronavirus 2. "However, no significant regulation was observed in the gene expression of CERS1, CERS3, CERS5, and CERS6 within the same COVID-19 group." (PMID 37566018, 2023).
dementia (1 paper, 2017). Loss of intellectual abilities interfering with an individual's social and occupational functions. "In humans, reduced CerS1 activity has been associated with myoclonus epilepsy and dementia, while mutation in SPT gene, the rate-limiting enzyme of the de novo synthesis, causes a hereditary peripheral neuropathy." (PMID 29311779, 2017).
dermatitis (1 paper, 2019). An inflammatory process affecting the skin. "In FAg-induced dermatitis, the expression of CerS1, CerS4, and CerS5 decreased, whereas the expression of CerS2 and CerS3 mildly increased with statistical significance." (PMID 30838224, 2019). "In IMQ-induced dermatitis, the expression of CerS1, CerS4, and CerS5 had a tendency to decrease, whereas the expression of CerS3 increased by 4.6-fold." (PMID 30838224, 2019).
diabetes (1 paper, 2024). "Ceramide levels, and particularly Cers1-derived C18-ceramides were previously found elevated in skeletal muscle upon high-fat diet, streptozotocin-induced diabetes and in obese, diabetic patients." (PMID 38506902, 2024).
endometriosis (1 paper, 2022). The growth of functional endometrial tissue in anatomic sites outside the uterine body. "However, gene expression involved in ceramide synthesis (SPHK1, ASAH1, and SGPP1) and autophagy (BECN1, LAMP, and PC3) were significantly lower in MGCs with endometriosis, whereas CERS1 and UGCG expression increased." (PMID 35992117, 2022). "Gene expression involved in ceramide synthesis (CERS1, SPTL1, and SMPD1) and autophagy (BECN1, LAMP, and PC3) were significantly higher in CCs with endometriosis according to FASN, BECN1, and LAMP protein expressions." (PMID 35992117, 2022).
glioblastoma (1 paper, 2024). The most malignant astrocytic tumor (WHO grade IV). "ER stress was also activated by CerS1 overexpression or C18-ceramide accumulation, which induces glioblastoma cell death via lethal autophagy in A172 and U251 human glioblastoma cell lines." (PMID 38894892, 2024).
Huntington disease (1 paper, 2022). Huntington disease (HD) is a rare neurodegenerative disorder of the central nervous system characterized by unwanted choreatic movements, behavioral and psychiatric disturbances and dementia. "The expression of the CerS1 primary band (∼40 kDa) was lower in Huntington’s disease caudate compared to controls when adjusted for both β-actin (−57.60%, P = 0.0025) and GAPDH (−23.34%, P = 0.0098)." (PMID 35169703, 2022). "Huntington’s disease subjects had a reduced expression of CerS1 localized to the caudate." (PMID 35169703, 2022). "Pearson’s correlation analyses were used to examine the relationship between CerS1 expression (primary band; ∼40 kDa) and age at death or CAG repeat length in Huntington’s disease subjects." (PMID 35169703, 2022).
Hypertension (1 paper, 2023). The presence of chronic increased pressure in the systemic arterial system. "Furthermore, this pathway plays a role in regulating ceramide metabolism and hypertension, with AKT activation upregulating ceramide synthase 1 (CerS1) and increasing ceramide production." (PMID 38137595, 2023).
leukemia (1 paper, 2020). A malignant (clonal) hematologic disorder, involving hematopoietic stem cells and characterized by the presence of primitive or atypical myeloid or lymphoid cells in the bone marrow and the blood. "Consistent with this, SKIP transfection resulted in up-regulation of expression of the same group of genes (again with the exception of CERS-1) in transfected leukemia cell lines compared with vector alone." (PMID 32161116, 2020). "Thus, we studied the expression of ceramide synthase genes (CERS-1, -2 -4 and -5) and PAFAH2 in primary AML samples and transfected leukemia cell lines." (PMID 32161116, 2020).
neuroblastoma (1 paper, 2017). Neuroblastoma (NB) is the most common solid, extracranial childhood tumor. "Downregulation of CERS1 in a neuroblastoma cell line induces ER stress and proapoptotic pathways, which points towards a role of CERS1 in neurodegeneration." (PMID 28566300, 2017).
osteosarcoma (1 paper, 2025). A usually aggressive malignant bone-forming mesenchymal neoplasm, predominantly affecting adolescents and young adults. "Mechanistically, inhibition of CERS1 restricted mitophagy to destroy the mitochondrial quality control in cisplatin‐resistant osteosarcoma cells, including mitochondrial membrane potential loss and unfavourable mitochondrial dynamics, rendering them susceptible to cisplatin‐induced apoptosis." (PMID 39834330, 2025). "The administration of a CERS1 inhibitor was found to resensitize CDDP‐resistant osteosarcoma cells to CDDP, inhibiting their proliferation, migration, invasion and inducing apoptosis." (PMID 39834330, 2025). "This regimen operates by inhibiting CERS1 to attenuate mitophagy, thus compromising the mitochondrial quality control mechanisms in CDDP‐resistant osteosarcoma cells, rendering them susceptible to CDDP‐induced apoptosis." (PMID 39834330, 2025). "BayeDEM, upon application to osteosarcoma datasets, demonstrated unparalleled accuracy in modelling the correlation between transcriptomic data and the mitophagy phenotype, identifying CERS1 as a critical gene regulating mitophagy in osteosarcoma." (PMID 39834330, 2025). "Taking an osteosarcoma sample as an illustration, CERS1's expression exerted the most substantial positive influence on the sample's BayeDEM prediction value of 5.58, propelling the model prediction towards a positive label indicative of high mitophagy." (PMID 39834330, 2025). "This study represents the inaugural confirmation that CERS1 is a critical regulator of mitophagy in osteosarcoma, with its overexpression leading to the hyperactivation of mitophagy." (PMID 39834330, 2025). "Inhibition of CERS1 sensitized cisplatin‐resistant osteosarcoma cells to cisplatin, restricting their growth, proliferation, invasion, migration and colony formation and inducing apoptosis." (PMID 39834330, 2025). "The present study utilized small molecule inhibitor P053 of CERS1 to downregulate the expression of CERS1 in the CDDP‐resistant osteosarcoma cell line (143B/CDDP)." (PMID 39834330, 2025). "One such gene, CERS1, was utilized to develop a drug combination strategy against cisplatin resistance, which was validated in an osteosarcoma‐resistant cell model, elucidating its molecular mechanism in combating drug resistance." (PMID 39834330, 2025). "BayeDEM identified CERS1 as the paramount gene positively regulating mitophagy in osteosarcoma." (PMID 39834330, 2025). "Consequently, inhibiting mitophagy by suppressing CERS1 disrupts the mitochondrial quality control mechanisms of osteosarcoma cells, thereby countering their CDDP resistance." (PMID 39834330, 2025). "Consequently, this research pioneers a novel combinatorial drug strategy aimed at mitigating CDDP resistance in osteosarcoma cells by inhibiting CERS1." (PMID 39834330, 2025). "Mechanistically, the inhibition of CERS1 disrupts mitochondrial quality control in CDDP‐resistant osteosarcoma cells through the inhibition of mitophagy, leading to the dissipation of mitochondrial membrane potential and unfavourable alterations in mitochondrial dynamics." (PMID 39834330, 2025). "Therefore, this study posits that targeting CERS1 to combat CDDP resistance in osteosarcoma may represent a promising therapeutic strategy." (PMID 39834330, 2025). "Gene expression comparisons between groups corroborated these findings, demonstrating significantly higher expressions of CERS1, FABP3 and NPDC1 in high‐mitophagy osteosarcoma, whereas PLEKHF1 and LILRA2 were significantly less expressed." (PMID 39834330, 2025). "CERS1, FABP3 and NPDC1 significantly propelled predictions towards high mitophagy, indicating these genes positively regulate mitophagy in osteosarcoma." (PMID 39834330, 2025). "More heartening, predicated on CERS1 identified through BayeDEM, this study has successfully devised and validated in preclinical cell models, a combinatory treatment regimen against CDDP‐resistant osteosarcoma." (PMID 39834330, 2025).
pancreatic ductal adenocarcinoma (1 paper, 2024). An infiltrating adenocarcinoma that arises from the epithelial cells of the pancreas. "Ceramide synthase 1 (CerS1), however pancreatic ductal adenocarcinoma (PDAC) remains as one of the most aggressive malignancies with a median 5 year-survival rate of 12%." (PMID 38720356, 2024).
Stroke (1 paper, 2021). Sudden impairment of blood flow to a part of the brain due to occlusion or rupture of an artery to the brain. "The increased expression of CerS1, detected only in the SHRSP, may be suggestive of an elevated bioavailability of cerebral ceramide which may reveal toxic and potentially associated with increased susceptibility to stroke." (PMID 33917593, 2021).
tauopathies (1 paper, 2019). "Inactivity of CERS1 protein leads to preferential degeneration of cerebellar Purkinje neurons, and Cers1 mRNA downregulation was reported in tauopathies, so a pathogenic role of CERS1 deficiency in SCA2 is likely." (PMID 31766565, 2019).
tongue squamous cell carcinoma (1 paper, 2021). A squamous cell carcinoma that arises from the tongue. "A total of 36% (9/25) of mice in the Cers1−/− group developed tongue squamous cell carcinoma compared with 12% (3/25) of mice in the Cers1 + /+ group." (PMID 33753723, 2021).
virus infection (1 paper, 2025). "As the in vitro overexpression of CerS4, but not CerS1, inhibited influenza virus replication, it is possible that specific ceramide subspecies synthesized in cells may be critical for the host defense against virus infection." (PMID 41217173, 2025).